PTBP1 (polypyrimidine tract binding protein 1)
Diseases named in the same sentence as PTBP1 in open-access papers (continued):
Sharing a sentence is not in itself a finding about the gene and the disease.
bladder cancer (22 papers, 2017 to 2026). "Studies have shown that in bladder cancer, PTBP1 promotes bladder cancer cell survival, facilitates splicing of oncogenic mutations, and promotes cell proliferation, migration, and invasion in vitro and in vivo." (PMID 40579921, 2025). "Also, the knockdown of PTBP1 caused the transition of LC3-I to LC3-II in breast and bladder cancer cells, while overexpression of PTBP1 reduced the transition of LC3-I to LC3-II." (PMID 40113750, 2025). "MiR-145 disrupts the Warburg effect by inhibiting the KLF4/PTBP1/PKMs pathway in bladder cancer cells, leading to significant inhibition of cell growth." (PMID 40689207, 2025). "HuR, also known as ELAVL1, is an RNA‐binding protein, in which lncHCG22 inhibits bladder cancer progression by destabilising HuR proteins to regulate PTBP1 levels." (PMID 40579921, 2025). "In bladder cancer, miR‐145 interferes with the Warburg effect by inhibiting the KLF4/PTBP1/PKMs pathway in bladder cancer cells to suppress tumour growth." (PMID 40579921, 2025). "PTBP1 is involved in the formation, invasion, and metastasis of bladder cancer, pancreatic cancer, lung cancer, ovarian cancer, and other cancers." (PMID 38071681, 2024). "By recognition of the poly(U) tracts in the 3’ untranslated regions (UTRs) of mRNA, PTBP1 enhances the alternative mRNA splicing of MEIS2-L and PKM2 variants to facilitate the lymphatic metastasis and proliferation of bladder cancer." (PMID 38341427, 2024). "SLC2A11–MIF modulates bladder cancer cell proliferation and metastasis through a PTBP1‐dependent mechanism." (PMID 39156764, 2024). "Recently, the RNA-binding protein and alternative pre-mRNA splicing factor, polypyrimidine tract binding protein 1 or PTBP1, has been shown to play a critical role in cancer progression (e.g., breast, colon and bladder cancer)." (PMID 36635500, 2023). "It has been reported in the literature that PTBP1 can be used as a biomarker for poor prognosis in bladder cancer, and PTBP3 as a therapeutic target for gastric cancer." (PMID 36203873, 2022). "Furthermore, luciferase assays demonstrated that miR-145 directly binds to the 3′UTR of KLF4, and that Warburg effect-related genes, such as PTBP1 and PKMs, are regulated by bladder cancer cells transfected with miR-145 or siR-KLF4." (PMID 40689207, 2025). "Moreover, mechanistic studies have revealed that PTBP1 regulates massive splicing events in bladder cancer." (PMID 39132499, 2024). "In bladder cancer, PTBP1 expression was found to be positively related to lymphatic metastasis, tumor stage, histological grade, and a poor patient prognosis in 104 patients with bladder cancer." (PMID 39132499, 2024). "HCG22 prevents the proliferation and metastasis of bladder cancer cells by controlling PTBP1." (PMID 36602530, 2023). "Furthermore, the inhibition of PTBP1 by miR-145, inhibits aerobic glycolysis and cell growth in human bladder cancer cells." (PMID 33621196, 2021). "Polypyrimidine tract binding protein 1, is a protein that has a function bladder cancer metastasis, and controls Meis2 and pyruvate kinase alternative splicing via direct binding to specific introns of these mRNA transcripts, contributing to bladder cancer development." (PMID 33402862, 2020). "In bladder cancer, Xie et al86 illustrated that PTBP1 promotes bladder cancer lymph node metastasis and cell proliferation via an alternative splicing dependent mechanism and that PTBP1 could be a novel prognostic marker and therapeutic target." (PMID 32808488, 2020). "This combination treatment could be a novel RNA-interference strategy through the systemic silencing of the Warburg effect-promoting driver oncogene PTBP1 in bladder cancer cells." (PMID 28106737, 2017). "The ectopic expression of miR-145 downregulated c-Myc expression at the translation level and decreased the PKM2/PKM1 ratio in both bladder cancer T24 and 253JB-V cells, thus suggesting that miR-145 controlled the cancer specific energy metabolism through the c-Myc/PTBP1/PKMs axis." (PMID 28106737, 2017).
bladder cancer (continued). "To investigate whether PTBP1 in bladder cancer samples was overexpressed, we examined paired samples from 12 bladder cancer patients by Western blot analysis." (PMID 28106737, 2017). "Mechanistically, CUL5 loss reduced the ubiquitination of PTBP1, which regulated alternative splicing of RUBCN pre-mRNA and led to an increase in the levels of the RUBCN-S isoform, thereby preventing immune evasion of bladder cancer cells by inhibiting autophagy." (PMID 41662369, 2026). "In bladder cancer, both lncHCG22 and lncMAFG‐AS1 can affect tumour progression through the HuR/PTBP1 axis." (PMID 40579921, 2025). "Therefore, PTBP1 may become a possible outcome-predictor for bladder cancer." (PMID 36203873, 2022). "Thus, consistent with our findings, the knockdown of PTBP1 (which increases the level of PTBP2) has been reported to lead to autophagy in colorectal and bladder cancer." (PMID 40113750, 2025). "For instance, our data indicated that PTBP1 was not involved in the splicing regulation of MESI and PKM, which induce tumor proliferation in bladder cancer, indicating the context‐dependent nature of PTBP1 target selection." (PMID 39287090, 2024).
gastric cancer (22 papers, 2017 to 2025). A primary or metastatic malignant neoplasm involving the stomach. "Bioinformatic analysis from TCGA gastric cancer database illustrated that PTBP1 expressions are positively associated with glycolysis enzymes expressions." (PMID 36447254, 2022). "Moreover, high PTBP1 expressions were associated with pool survival rates of gastric cancer patients." (PMID 36447254, 2022). "Previous studies have reported that N4-acetylcytidine drives glycolysis in gastric cancer via a NAT10/SEPT9/HIF-1α positive feedback loop, and the lncRNA CCAT1 facilitates the progression of gastric cancer via PTBP1-mediated enhancement of glycolysis." (PMID 40796546, 2025). "Previous studies have highlighted the tumor-promoting role of PTBP1 in various gynecological cancers, including breast and cervical cancers, as well as in other malignancies such as liver, colon, gastric cancers, and lung adenocarcinoma." (PMID 41313521, 2025). "Some studies have revealed the critical role of PTBP1 in the occurrence and development of gastric cancer." (PMID 40579921, 2025). "To evaluate the effect of PTBP1 on the metastatic ability of gastric cancer cells in vivo, we established a liver metastasis model of gastric cancer in nude mice." (PMID 38247832, 2024). "To elucidate the molecular mechanisms regulating gastric cancer metastasis, we investigated the downstream target genes of PTBP1." (PMID 38247832, 2024). "LncRNA CCAT1 promotes the progression of gastric cancer through PTBP1-mediated glycolysis enhancement." (PMID 39588377, 2024). "This suggested that PGK1 played an important role in the promotion of gastric cancer cell migration by PTBP1." (PMID 38247832, 2024). "Altogether, these data indicate that PTBP1 is an essential modulator for the maintenance of gastric cancer stem-cell properties." (PMID 36635500, 2023). "The relationship between PTBP1 and proliferation of gastric cancer cells was further detected by subcutaneous tumor transplantation." (PMID 37670313, 2023). "Particularly, PTBP1 has been reported to function as an important regulator in cancers, including glioma, breast cancer, gastric cancer, lung cancer, renal cell carcinoma, and colon cancer." (PMID 36447254, 2022). "In this study, we described a SNHG16-miR-506-3p-PTBP1-glycolysis-5-Fu-resistant axis in gastric cancer cells." (PMID 36447254, 2022). "As we expected, gastric cancer cells with either SNHG16 or PTBP1 silencing displayed increased 5-Fu sensitivity compared with control cells." (PMID 36447254, 2022). "SNHG16 downregulates miR-506-3p as a ceRNA to de-repress its miRNA target, PTBP1, which upregulates glycolysis key enzymes expressions via binding to the 3′UTRs of enzymes mRNAs, leading to 5-Fu resistance in gastric cancer cells." (PMID 36447254, 2022). "In this study, the biological roles of lncRNA SNHG16 and PTBP1 in 5-Fu-resistant gastric cancer will be investigated." (PMID 36447254, 2022). "Taken together, these results demonstrated that PTBP1 promoted glucose metabolism of gastric cancer cells through upregulating the glycolysis key enzymes." (PMID 36447254, 2022). "We further detected a significantly reverse correlation between miR-506-3p and PTBP1 mRNA expressions in gastric cancer tissues." (PMID 36447254, 2022). "To gain an in-depth understanding of the roles of SNHG16 and PTBP1 in 5-Fu-resistant gastric cancer, we established a 5-Fu-resistant gastric cancer cell line from AGS cell by gradual exposing cells to increased concentrations of 5-Fu for 3 months." (PMID 36447254, 2022). "Overexpression of miR-506-3p effectively blocked PTBP1 protein expressions in gastric cancer cells by Western blot." (PMID 36447254, 2022). "The expression levels of TGFB1, TGFB2, ZEB1 and PTBP1 were detected by qRT-PCR in 92 pairs of gastric carcinoma specimens and adjacent normal tissues (Cohort 2)." (PMID 34706749, 2021). "We performed rescue assays to verify whether PTBP1 promotes gastric cancer cell migration in a PGK1-dependent manner." (PMID 38247832, 2024).
gastric cancer (continued). "Finally, tissue microarray data from clinical samples were used to further explore the expression of PTBP1 in patients with gastric cancer and its correlation with prognosis." (PMID 37670313, 2023). "Therefore, the use of c-Myc inhibitors provides ideas for the treatment of gastric cancer and reduction of drug resistance until inhibitors of PTBP1 for gastric cancer are available." (PMID 36635500, 2023). "Taken together, the PTBP1/c-Myc signalling axis may be an attractive target for developing new therapeutics for the treatment of gastric cancer." (PMID 36635500, 2023). "Furthermore, we will assess the mechanisms for the PTBP1-mediated glucose metabolism in gastric cancer." (PMID 36447254, 2022). "Importantly, restoration of PTBP1 in miR-506-3p overexpressing gastric cancer cells recovered the glucose uptake and lactate product." (PMID 36447254, 2022). "Accumulating evidence revealed that lncRNA SNHG16 and PTBP1 were apparently associated with poor prognosis and malignant phenotypes of multiple cancers, we started to investigate the clinical relevance of SNHG16 and PTBP1 in gastric cancer." (PMID 36447254, 2022). "Given that SNHG16 and miR-506-3p-PTBP1-glycolysis inversely modulated 5-Fu sensitivity of gastric cancer, we examined whether SNHG16 accelerated 5-Fu resistance through suppressing the miR-506-3p-PTBP1-glycolysis axis." (PMID 36447254, 2022). "In summary, these results demonstrated SNHG16 and PTBP1 are positively associated with 5-Fu resistance in gastric cancer, suggesting targeting SNHG16 and PTBP1 could contribute to enhancing the cytotoxicity of chemotherapeutic agents." (PMID 36447254, 2022). "In addition, ILF3‐AS1 functions as a ceRNA to regulate PTBP1 expression by sponging miR‐29a in gastric cancer." (PMID 34427967, 2021). "Reports revealed that microRNA-133b could silence PKM-splicer PTBP1, leading the inhibition of growth of human gastric cancer cells." (PMID 28232943, 2017). "26S proteasome non‐ATPase regulatory subunit 14, a deubiquitinating enzyme, is highly expressed in gastric cancer tissues, and it co‐localises and endogenously interacts with PTBP1, which can promote gastric cancer development by stabilising the molecular structure domain of PTBP1." (PMID 40579921, 2025). "Gastric cancer (GC) is a prevalent malignant tumor, and the RNA-binding protein polypyrimidine tract-binding protein 1 (PTBP1) has been identified as a crucial factor in various tumor types." (PMID 39153986, 2024). "However, PTBP1 inhibitors are still in a vacant state in gastric cancer treatment, and our results confirm that PTBP1 is critical to the progression of gastric cancer, therefore PTBP1 inhibitors suitable for gastric cancer targets are urgently exploited." (PMID 36635500, 2023). "We then asked whether PTBP1 modulates glucose metabolism rate of gastric cancer cells." (PMID 36447254, 2022). "Another study found that the knockdown of PTBP1 significantly inhibited the proliferation, migration, and invasion of gastric cancer cells in vitro and that PTBP1 could maintain the tumorigenic activity and stem cell properties of gastric cancer in vitro and in vivo." (PMID 40579921, 2025). "At present, the role of PTBP1 in gastric cancer (GC) is still unknown and worthy of further investigation." (PMID 37670313, 2023). "To explore the roles of SNHG16 and PTBP1 in 5-Fu resistance, we assessed the effects of silencing SNHG16 and PTBP1 on 5-Fu sensitivity of gastric cancer cell." (PMID 36447254, 2022). "CircFOXP1 interacts with PTBP1 to accelerate the Warburg effect in gallbladder cancer, circMYBL2 modulates FLT3 translation by recruiting PTBP1 in AML and circDLST sponges miR-502-5p to enhance the metastasis of gastric cancer." (PMID 34872582, 2021). "PTBP1 negatively regulates this process, and reducing the expression levels of RAGE and HMGB1 can inhibit the glycolysis, proliferation, and migration ability of gastric cancer cells." (PMID 40579921, 2025).
gastric cancer (continued). "However, the precise molecular mechanisms for the PTBP1-regulated glycolysis and the roles of PTBP1 in 5-Fu resistance in gastric cancer cells have not yet been elucidated." (PMID 36447254, 2022).
lung carcinoma (18 papers, 2019 to 2025). "A previous study by Cho and colleagues demonstrated that PTBP1 contributes to AXL mRNA degradation by targeting its 5’UTR in lung cancer cells." (PMID 41313521, 2025). "The overexpressed PKM2 and TRIB2 increased the expression of GLUT1, LDHA, and PTBP1 to promote the aerobic glycolysis in lung cancer cells." (PMID 35790734, 2022). "Consistently, miR-133a is silenced by epigenetic factors in lung cancer cells, leading to upregulation of its target gene PTBP1 and accelerated lung cancer cell growth and metastasis." (PMID 36139427, 2022). "It is reported that PTBP1 promotes lung cancer metastasis by regulating the alternative splicing of Mena mRNA." (PMID 36203873, 2022). "To further validate the correlation between PTBP1 expression and overall survival, we examined the prognosis of PTBP1 in lung cancer by clinical samples from Yunnan Cancer Hospital (N=181)." (PMID 35600383, 2022). "Regarding lung cancer, we found a correlation between high expression of PTBP1 and poor OS prognosis (P = .029) and poor DFS (P = .042) specific for LUAD but not for lung squamous cell carcinoma." (PMID 36595978, 2022). "Stable knockdown of PTBP1 results in progressively shortened telomere length in H1299 and H920 lung cancer cells." (PMID 30568224, 2019). "As a result, up-regulation of AXL expression by PTBP1 siRNA was observed in other lung cancer cell lines, including A549 and H1299." (PMID 31729427, 2019). "PTBP1 was observed to be negatively correlated with AXL expression in lung cancer tissues (r = −0.7266, P < 0.01)." (PMID 31729427, 2019). "In lung cancer cells, miR‐133a inhibits lung cancer growth and metastasis by binding to PTBP1." (PMID 40579921, 2025). "Also in lung cancer, it has been shown that PTBP1 binds to the 5′ UTR of the mRNA of the transmembrane receptor tyrosine kinase AXL causing a decrease in its stability and thus affecting tumour progression." (PMID 40579921, 2025). "Moreover, PTBP1 can play a pro‐oncogenic role in lung cancer by promoting the cyclization of circular RNAs (circRNAs) with pro‐oncogenic function." (PMID 40579921, 2025). "It has been found that PTBP1 binds to the flanking intron of circGLIS3 to promote the production of the oncogenic factor circGLIS3, which promotes tumour cell proliferation, migration, and invasion and enhances the progression of non‐small cell lung cancer." (PMID 40579921, 2025). "In general, our study reveals the role of LGG/SNHG17/PTBP1 in attenuating lung cancer cell proliferation and EMT progression, and suggests that SNHG17 may serve as a novel therapeutic target for RIPF." (PMID 36635762, 2023). "However, when PTBP1 was knocked down in lung cancer cells, PTBP2 levels went up to compensate for reduced PTBP1 levels, and PTBP2 interacts with NOVA1 and resulted in reduced FL TERT and telomerase." (PMID 37531400, 2023). "The analysis revealed that miRNA-195-5p was negatively correlated with PTBP1 in lung cancer." (PMID 35600383, 2022). "Hence, PTBP1 plays an important role in the immune response, as well as the development and progression of lung cancer." (PMID 35600383, 2022). "The results indicated that PTBP1, as an important lung cancer stem cell marker gene, may be a target gene of miRNA-195-5p." (PMID 35600383, 2022). "In addition, TGFβ induces the expression of polypyrimidine tract-binding protein 1 (PTBP1), involved in exon 11a skipping, enhancing migration and invasion of lung cancer cells as well as EMT features in A549 cells." (PMID 33672325, 2021). "Although modest, PTBP1 KD in both lung cancer lines increased the critically short telomeres." (PMID 30568224, 2019).
lung carcinoma (continued). "In addition, PTBP1 can also play a pro‐lung cancer role by regulating the stability of mRNA of downstream target genes, and PTBP1 can promote the progression of lung cancer through the binding of RRM1 to AXL mRNA, resulting in its unstable regulation of AXL expression." (PMID 40579921, 2025). "Specifically, we determined that PTBP1 interacts with NOVA1 to promote FL TERT and telomerase activity in lung cancer cells." (PMID 37531400, 2023). "We focused on H1299 and H920 lung cancer cells because both lines have robust NOVA1 and PTBP1 expression and showed changes in telomerase activity following transient knockdown of PTBP1." (PMID 30568224, 2019). "Moreover, we have demonstrated that PTBP1 may inhibit tumorigenesis of lung cancer cells in vivo." (PMID 31729427, 2019). "In lung cancer, PTBP1 can promote the Warburg effect in lung cancer cells by selectively splicing and promoting the conversion of PKM1 to PKM2, and circRNA EPB41L2 can play an anti‐tumour role by promoting the ubiquitination degradation of PTBP1." (PMID 40579921, 2025). "The luciferase assay showed that transfection with miR-195-5p mimics significantly reduced the relative luciferase activity of PTBP1-3′-UTR-wild-type-treated lung cancer cells; however, it did not affect that of PTBP1-3′-UTR-mutation-treated lung cancer cells." (PMID 35600383, 2022). "The mean AXL score was higher in the lung cancer cohort than in the normal cohort (217.9 ± 37 vs 120.8 ± 29.9, P < 0.01), whereas the mean PTBP1 H-score was lower in the lung cancer cohort than in the normal cohort (57.8 ± 17.8 vs 116.7 ± 22.4, P < 0.01)." (PMID 31729427, 2019). "In addition, in lung cancer cells acquiring resistance to gefitinib or erlotinib due to AXL, it is highly likely that up-regulation of PTBP1 would recover their drug sensitivity." (PMID 31729427, 2019).